TMED5 (transmembrane p24 trafficking protein 5)
Description:
Potential role in vesicular protein trafficking, mainly in the early secretory pathway. Required for the maintenance of the Golgi apparatus; involved in protein exchange between Golgi stacks during assembly. Probably not required for COPI-vesicle-mediated retrograde transport.
Synonyms: p24gamma2; CGI-100; p24g2; p28
Tractability: Antibody: UniProt predicts a signal peptide or a membrane-spanning region. PROTAC: ubiquitination databases record sites on it; its protein half-life has been measured.
Gene: Protein-coding gene on chromosome 1 (93,149,742 to 93,180,516, reverse strand). Ensembl gene ENSG00000117500.
Subcellular location: Endoplasmic reticulum membrane; Golgi apparatus, cis-Golgi network membrane; Endoplasmic reticulum-Golgi intermediate compartment membrane
Pathways (Reactome):
Signal Transduction: WNT ligand biogenesis and trafficking
Gene Ontology:
Molecular function: protein binding
Biological process: Golgi ribbon formation; endoplasmic reticulum to Golgi vesicle-mediated transport
Cellular component: cis-Golgi network; endoplasmic reticulum exit site; endoplasmic reticulum-Golgi intermediate compartment; endoplasmic reticulum membrane; endoplasmic reticulum-Golgi intermediate compartment membrane; Golgi apparatus
Genetic constraint (gnomAD): Loss-of-function variants: 18 observed, 15.89 expected, observed/expected ratio (o/e) 1.13, 90% interval 0.78 to 1.66. The upper end of that interval is the gene's LOEUF score, 1.66, which puts it in group 6 of 6, group 1 being the genes least tolerant of losing a copy. Missense variants: 208 observed, 237.63 expected, observed/expected ratio (o/e) 0.88, 90% interval 0.78 to 0.98. Synonymous variants: 85 observed, 91.24 expected, observed/expected ratio (o/e) 0.93, 90% interval 0.78 to 1.12.
Homologues: Orthologues: chimpanzee TMED5 (99% identical), macaque TMED5 (99% identical), rabbit TMED5 (97% identical), pig TMED5 (95% identical), mouse Tmed5 (90% identical), rat Tmed5 (90% identical), dog TMED5 (78% identical), tropical clawed frog tmed5 (68% identical), zebrafish tmed5 (66% identical), Drosophila melanogaster p24-1 (23% identical), Caenorhabditis elegans tmed-12 (12% identical). Paralogues in human: TMED1 (52% identical), TMED7 (29% identical), TMED3 (28% identical), TMED2 (24% identical), TMED4 (21% identical), TMED9 (21% identical), TMED6 (21% identical), TMED10 (17% identical).
Diseases named in the same sentence as TMED5 in open-access papers:
TMED5 is named in the same sentence as 12 diseases in open-access papers, as found by Europe PMC text mining. Sharing a sentence is not in itself a finding about the gene and the disease. The quoted sentences say what the papers report.
cervical cancer (6 papers, 2021 to 2022). A primary or metastatic malignant neoplasm involving the cervix. "Evidence showed that the up-regulation of TMED5 in cervical cancer cells promoted malignant behavior and nuclear autophagy, affecting the progression of malignant tumors." (PMID 35754792, 2022). "Increased TMED5 expression facilitates cell proliferation, invasion and migration in cervical cancer cells." (PMID 35832191, 2022). "Our results identified that TMED5 was directly targeted and inhibited by miR-183-5p, and TMED5 knockdown phenocopied miR-183-5p overexpression in suppressing cervical cancer development and angiogenesis." (PMID 34404391, 2021). "Analysis of TMED5 expression in cervical cancer showed that TMED5 mRNA and protein levels were significantly promoted in tumor samples and cancer cells compared with the corresponding normal controls." (PMID 34404391, 2021). "In addition, a study had also shown that TMED5 could interact with WNT7B in HeLa cells to activate the wnt/β-catenin pathway in cervical cancer." (PMID 35281863, 2022). "Meanwhile, TMED5 plays a tumor-promoting role in the malignant development of cervical cancer by activating the Wnt7b/β-catenin signaling pathway, while Mir-183-5p can directly target TMED5 and inhibit its expression, so as to inhibit the occurrence of cervical cancer." (PMID 34911543, 2021). "In addition, we examined the mRNA expression of RNF4, OCIAD1, TMED5, DHX15, MED28, and LETM1 in TMEM33 knockdown cervical cancer cells." (PMID 35832191, 2022). "Moreover, TMED5 was directly targeted and inhibited by miR-183-5p through the perfect complementary sites in TMED5 3′UTR, and TMED5 knockdown phenocopied miR-183-5p overexpression in suppressing cervical cancer development and angiogenesis." (PMID 34404391, 2021).
bladder cancer (1 paper, 2021). "TMED5, located at chromosomal region 1p21-22, was associated with the pathogenesis of myeloma and bladder cancer." (PMID 34404391, 2021).
cervical (1 paper, 2021). "In order to demonstrate whether inhibition of TMED5 by miR-183-5p was responsible for the regulatory effects of miR-183-5p on cervical carcinogenesis and angiogenesis, we adopted a rescue experiment by increasing TMED5 expression in SiHa and HeLa cells." (PMID 34404391, 2021).
colon cancer (1 paper, 2014). "Although the homolog of TMED3 in Drosophila (logjam; Strating & Martens, 2009) may not be involved in Wnt signaling, we tested for this possibility in human colon cancer cells since p24 proteins are multifunctional and TMED5 affects WNT1 secretion in 293T cells." (PMID 24920608, 2014).
lung carcinoma (1 paper, 2014). "According to Oncomine database DR1, EVI5, TMED5 and RPL5 are co-amplified also in brain, colon, lung cancer and melanoma, indicating that amplification of 1p21-22 may be a recurrent alteration in several different types of cancers." (PMID 25135188, 2014).
mild cognitive impairment (1 paper, 2025). "Numerous TMED proteins have been shown to be dysregulated in mild cognitive impairment (MCI) and AD brains: While TMED5 expression increases in the AD parietal cortex, expression of both TMED4 and TMED9 decreases in the AD frontal cortex." (PMID 41103078, 2025).
cancer (4 papers, 2014 to 2022). A tumor composed of atypical neoplastic, often pleomorphic cells that invade other tissues. "As would be expected, elevated expression of TMED5 significantly abrogated miR-183-5p overexpression-mediated anti-proliferation and pro-apoptosis effects in the two cancer cell lines." (PMID 34404391, 2021). "Moreover, the TMEM33 expression level was remarkably positively correlated with similar genes of RNF4, OCIAD1, TMED5, DHX15, MED28 and LETM1, which have been reported to be implicated in tumorigenesis of various cancers." (PMID 35832191, 2022). "Moreover, endogenous TMED5 mRNA and protein levels were strongly promoted by miR-183-5p depletion and inhibited as a result of miR-183-5p overexpression in the two cancer cell lines." (PMID 34404391, 2021).
tumor (4 papers, 2021 to 2022). "The RT-PCR also showed that TMED5 was overexpressed in tumor tissues compared to adjacent." (PMID 35281863, 2022). "Additionally, in vivo assays implied the involvement of the circ_0018289/miR-183-5p/TMED5 regulatory network in tumor growth, and the direct evidence should be further elucidated in further work." (PMID 34404391, 2021). "Importantly, TMED5 mRNA level inversely correlated with miR-183-5p expression and positively correlated with circ_0018289 expression in tumor samples." (PMID 34404391, 2021). "Furthermore, our data showed that the circ_0018289/miR-183-5p/TMED5 axis contributed to an elevated expression of VEGFA and FGF2, two angiogenesis inducers, leading to induction of tumor-associated angiogenesis." (PMID 34404391, 2021).
TMED5 also shares sentences with these, for which no sentence is quoted: gastric cancer (1 paper); melanoma (1); myeloma (1); periodontitis (1).